LEP (leptin)
Diseases named in the same sentence as LEP in open-access papers (continued):
Sharing a sentence is not in itself a finding about the gene and the disease.
neuroblastoma (20 papers, 2011 to 2024). Neuroblastoma (NB) is the most common solid, extracranial childhood tumor. "Second, to carefully verify the stimulatory effect of leptin on neuroblastoma aggressiveness, leptin-associated neuroblastoma progression should be further evaluated in relevant animal models (e.g., high-fat diet-fed mice)." (PMID 37895840, 2023). "To experimentally verify the results of transcriptome analysis, we evaluated the impact of leptin on several characteristics associated with the aggressiveness of neuroblastoma cells, including proliferation rate, motility, changes in cellular morphology, adhesiveness, and modulation of EMT markers." (PMID 37895840, 2023). "Next, we asked whether SM could modulate leptin-induced changes in the metastasis-associated characteristics of neuroblastoma cells." (PMID 37895840, 2023). "Interestingly, patients with International Neuroblastoma Staging System (INSS) stage 4S, which is characterized by a favorable outcome, demonstrated lower expression of leptin compared to INSS stage 4 high-risk neuroblastoma patients." (PMID 37895840, 2023). "Considering the crucial role of the SOS/MEK1/ERK2 signaling axis in leptin signaling in various cancers (not only in neuroblastoma), the obtained results encourage further investigation of SM as a potent inhibitor of the tumor-promoting potency of leptin." (PMID 37895840, 2023). "SM was found to abrogate this effect and obviously enhance the expression of ZO-1 in leptin-stimulated neuroblastoma cells." (PMID 37895840, 2023). "The data presented here provide, for the first time, evidence that leptin is involved in the progression of neuroblastoma." (PMID 37895840, 2023). "In our study, for the first time, transcriptome analysis of neuroblastoma tissue demonstrated that the level of leptin is elevated in neuroblastoma patients along with the severity of the disease and is inversely correlated with patient survival." (PMID 37895840, 2023). "In the next step of the study, we explored the effect of SM and its derivatives on the growth-stimulating property of leptin in neuroblastoma cells." (PMID 37895840, 2023). "Despite the proven tumorigenic effect of leptin on epithelial-derived cancers, its impact on the aggressiveness of neural crest-derived cancers, notably neuroblastoma, remains largely unexplored." (PMID 37895840, 2023). "Taken together, our findings in murine Neuro2a cells provide novel evidence of the stimulatory effect of leptin on the aggressiveness of neuroblastoma, which requires further detailed studies in human neuroblastoma cells and relevant animal models." (PMID 37895840, 2023). "The available data only demonstrated the effect of leptin on cell proliferation and its protective potency in neuroblastoma cells against a range of cytotoxic stimuli." (PMID 37895840, 2023). "The performed reanalysis of transcriptomic data from GSE49710 clearly demonstrates that intratumoral expression of leptin markedly increases with neuroblastoma grade and is correlated with poor survival in neuroblastoma patients." (PMID 37895840, 2023). "It was found that the median expression of leptin in tumor nodes increased with the progression of neuroblastoma." (PMID 37895840, 2023). "The influence of leptin on the proliferation, motility, morphology, adhesiveness, and neuritogenic capacity of mouse neuroblastoma Neuro2a cells was explored." (PMID 37895840, 2023). "Our findings clearly indicate that leptin significantly enhances the proliferation and motility of murine Neuro2a neuroblastoma cells, while reducing their adhesion to ECM proteins." (PMID 37895840, 2023). "Although these experiments were performed only in mouse cells, the results obtained provide valuable insights into the relationship between leptin and neuroblastoma progression that need to be further explored in human neuroblastoma cells." (PMID 37895840, 2023).
neuroblastoma (continued). "Reanalysis of transcriptomic data showed that the expression of leptin was increased in advanced neuroblastoma and was inversely correlated with patient survival." (PMID 37895840, 2023). "This study aimed to analyze the pro-tumor potency of leptin, one of the most relevant adipokines, in relation to neuroblastoma cells and explore the pharmacological potential of cyanoenone-bearing triterpenoids in modulating this interconnection." (PMID 37895840, 2023). "The treatment of murine Neuro2a neuroblastoma cells with leptin significantly stimulated their proliferation and motility and reduced cell adhesion, thus rendering the phenotype of neuroblastoma cells more aggressive." (PMID 37895840, 2023). "The present study examined the effect of homocysteine on leptin signaling in SH-SY5Y neuroblastoma cells expressing the leptin receptor Ob-Rb." (PMID 36512575, 2022). "Uptake of Aβ is also modulated by leptin as LRP1-mediated uptake of Aβ is elevated after treatment of human SHSY-5Y neuroblastoma cells with leptin." (PMID 30386207, 2018). "Levels of transcripts of SOCS3 was found to be increased with increased survival of neuroblastoma with leptin suggesting its role in neuroblastoma." (PMID 29278364, 2017). "In conclusion, we herein demonstrated the important role of GRP78 in potentiating leptin signaling in a human neuroblastoma cellular model." (PMID 27677243, 2016). "There are studies reported that leptin exerts anti-apoptotic activity in T cells, monocytes, neuroblastoma cells, neutrophils, hippo-campal neurons and murine dendritic cells, while inducing apoptosis in human bone marrow stromal cells." (PMID 27482353, 2016). "In conclusion, this is the first study to show that leptin activated the UPR by specifically increasing the expression of GRP78 in a human neuroblastoma cell model." (PMID 25403445, 2014). "Thus, the obtained results clearly indicate that the revealed pro-metastatic effect of leptin in neuroblastoma cells is EMT-independent." (PMID 37895840, 2023). "Based on these findings, we decided to investigate whether leptin is expressed in human neuroblastoma tissues." (PMID 37895840, 2023). "Indeed, treatment of Neuro2a mouse neuroblastoma cells with leptin increased their proliferation, which is consistent with the previously reported mitogenic effect of leptin on SH-SY5Y human neuroblastoma cells." (PMID 37895840, 2023). "We believe that leptin, produced by tumor cells or their microenvironment, may act as an autocrine and paracrine factor, enhancing the growth and invasion of neuroblastoma." (PMID 37895840, 2023). "However, SM was able to restore the adhesion of leptin-stimulated neuroblastoma cells to ECM proteins to nearly the control level." (PMID 37895840, 2023). "Taken together, our results highlight the targeting of leptin signaling as a novel therapeutic strategy in NC-derived cancers and demonstrate that SM can be considered a promising lead compound for drug development for neuroblastoma treatment." (PMID 37895840, 2023). "Given that vimentin is a crucial regulator of the β1 integrin adhesive machinery, the observed downregulation of vimentin induced by leptin could explain its inhibitory effect on the adhesiveness of neuroblastoma cells." (PMID 37895840, 2023). "Further study revealed that the 27-OHC reduced leptin expression in human neuroblastoma SH-SY5Y cells by inducing endoplasmic reticulum stress that activates C/EBP homologous protein, which has a negative regulation on C/EBPα, a transcription factor necessary for leptin expression." (PMID 35464321, 2022). "Leptin has been shown to prevent the apoptosis of eosinophils, neutrophils from human adult, T lymphocytes, monocytes, NK cells, and other hematopoietic cells, neuroblastoma cells, and hepatic stellate cells." (PMID 23383125, 2013).
neuroblastoma (continued). "In light of these data, our study aimed to address two specific questions: first, whether leptin is capable of increasing the aggressiveness of neuroblastoma, and second, whether cyanoenone-bearing triterpenoids can suppress the tumor-promoting effect of leptin on neuroblastoma cells." (PMID 37895840, 2023). "Performed Kaplan–Meier survival analysis demonstrated a significant correlation between high leptin mRNA level and worse overall survival in neuroblastoma patients, which could indicate the ability of leptin to enhance the malignant characteristics of neuroblastoma." (PMID 37895840, 2023). "To assess the effect of homocysteine on leptin signaling, we pre-treated the SH-SY5Y-Ob-Rb human neuroblastoma cell line with homocysteine at 3 and 10 mM and analyzed the phosphorylation of STAT3 induced by leptin (0.01 μg/mL, equal to 0.6 nM)." (PMID 36512575, 2022). "To test leptin’s effect on Hsp10 expression in vitro, we used the transgenic cell line SH-SY5Y (neuroblastoma cells) overexpressing the long isoform of leptin receptor (ObRb)." (PMID 33946318, 2021). "Leptin (0.5 μg/mL, 15 min) was administered to a SH-SY5Y human neuroblastoma cell line stably transfected with Ob-Rb leptin receptor (SH-SY5Y Ob-Rb), and the cells were analyzed for STAT3 and STAT5 activation." (PMID 27746736, 2016). "ER stress impaired leptin-induced STAT3 activation and this effect was reversed by flurbiprofen in the SH-SY5Y-Ob-Rb neuroblastoma cell line." (PMID 24421337, 2014). "The pretreatment of neuroblastoma cells with LY294002 and PD98059 did not alter the leptin-mediated phosphorylation of STAT3, which indicated that the leptin-induced activation of STAT3 was independent of PI3K and MEK." (PMID 25403445, 2014). "In vitro, leptin has been shown to increase FAAH activity in T lymphocytes, although not in neuroblastoma cells, and our results suggest that in vivo leptin does not significantly affect FAAH activity in adipocytes." (PMID 21813022, 2011).
scoliosis (20 papers, 2009 to 2025). A congenital or acquired spinal deformity characterized by lateral curvature of the spine. "Recently, a large prospective cohort study reported that reductions in leptin, lean and fat mass were associated with an increased risk of scoliosis in adolescents, which provided supporting evidence for the potential link between leptin and AIS13." (PMID 31748652, 2019). "Although these were not measured in the current study, other authors emphasize that the role of leptin in the pathogenesis of scoliosis may be associated with the important difference between spine growth velocity compared to the extremities and a lower bioavailability." (PMID 26828519, 2016). "Studies have also explored the role of leptin, a hormone crucial for regulating bone and energy metabolism in children, in the mechanisms of scoliosis." (PMID 40401075, 2025). "In our present study, this parameter was significantly related to the scoliosis severity and leptin level." (PMID 32878212, 2020). "Women students with low BMI may have lower leptin levels, this may be one of the reasons for the higher scoliosis prevalence among female students." (PMID 35923961, 2022). "In addition, the anthropometric character of scoliosis patients is thought to be related to the pathophysiology of scoliosis, namely the influence of leptin as well as somatic and authonomic nerve disharmony." (PMID 32183373, 2020). "Leptin is one of the main hormones suspected of being involved in scoliosis." (PMID 26186348, 2015). "Nucleus pulposus cells isolated from scoliosis patients were treated with 10 ng/mL of leptin." (PMID 24441571, 2014). "However, scoliosis may be less likely in obese adolescents because of abnormal leptin bioavailability." (PMID 36561865, 2022). "In AIS girls with lower spine scoliosis, the LHS concept postulates that the left-right iliac length asymmetries result from an adverse hormetic response to leptin in the hypothalamus, a suggestion considered plausible [Calabrese E, personal communication]." (PMID 19566930, 2009). "Later, we examine whether the scoliosis of these three mouse models may be markers of stress reactions involving the hypothalamus rather than crucial influences for scoliosis development (see Scientific basis of leptin-hypothalamic-sympathetic nervous system (LHS) concept, items 11 & 12)." (PMID 19878575, 2009). "He argues that the low effect of leptin on the CNS in individuals with AIS may explain the different patterns of cerebral cortex thinning seen in patients with scoliosis during adolescence, which may be primary (i.e., pathogenetic) or secondary (i.e., adaptation) to the development of scoliosis." (PMID 36235665, 2022). "Fourthly, the low leptin effect on the CNS in AIS subjects may explain the different thinning pattern of the cerebral cortex observed in patients with AIS during adolescence, which may be primary (i.e. pathogenetic) or secondary (i.e. adaptation) to the development of scoliosis." (PMID 27252984, 2016).
epilepsy (19 papers, 2007 to 2025). A brain disorder characterized by episodes of abnormally increased neuronal discharge resulting in transient episodes of sensory or motor neurological dysfunction, or psychic dysfunction. "The aim of this study was to review the association between leptin and cerebral neuronal function, in particular its anticonvulsant or convulsant effects and the possible therapeutic role for treating epilepsy." (PMID 30185147, 2018). "The association between leptin and brain function demonstrates the importance of peripheral metabolic hormones on central nervous system and opens a new way for the development of novel therapeutic interventions in diseases like epilepsy." (PMID 30185147, 2018). "At this point, it is important to note that the peripheral effects of leptin may have relevant implications on susceptibility to epilepsy." (PMID 30185147, 2018). "Changes in blood leptin levels can be considered as a perspective biomarker of AIMetS in patients with epilepsy and epileptic syndromes." (PMID 40217882, 2025). "Although our study revealed that leptin and cannabinoids exert their effects on epilepsy through the oxidative system, further molecular and biochemical studies are needed to further elucidate the molecular mechanisms." (PMID 38775505, 2024). "This article will discuss the correlation among various biological functions and complex signaling mechanisms of leptin and adiponectin, the way how these two adipokines regulate the metabolism and energy homeostasis and the pathological processes of epilepsy." (PMID 36797447, 2023). "Intraventricular administration of leptin at a dose of 1 μg in a rat model with penicillin-induced epilepsy increases the mean frequency of epileptiform activity, but never changes its amplitude." (PMID 36797447, 2023). "In particular, we discuss the dual effects of leptin in epilepsy and the relationship between antiepileptic drugs and changes in the levels of these two adipokines." (PMID 36797447, 2023). "Reports on leptin's pro-convulsant and anticonvulsant effects have indicated specific roles of leptin in different epilepsy models and signaling pathways." (PMID 36797447, 2023). "Adipokines, including leptin, visfatin, adiponectin, and interleukin-6 (IL)-6, play multiple roles in the pathophysiology of epilepsy and febrile seizures (FS)." (PMID 33042001, 2020). "Unlike traditional antiepileptic drugs, significant progress was made recently in understanding the effects and mechanisms of endocrine modulators, such as melatonin, leptin and ghrelin, on pediatric neurological diseases, particularly epilepsy." (PMID 31440210, 2019). "The role of leptin in the pathogenesis of epilepsy is getting more and more attention in clinical and basic research." (PMID 30319532, 2018). "Research was made through the Medical Subject Headings (MESH) terms: MeSH keywords in Pubmed: (((“Epilepsy”[Mesh]) AND “Leptin”[Mesh]) OR “Adipose Tissue”[Mesh]) OR “Hypothalamus”[Mesh]." (PMID 30185147, 2018). "The objective of this article was to analyze the possible effects of leptin on the pathophysiology of epilepsy, comparing the findings of animal models, which demonstrated both convulsive and non-convulsive actions." (PMID 30185147, 2018). "On the other hand, enough endocrine products such as leptin by adipose tissue are effective in epilepsy." (PMID 27057188, 2016). "More interesting for epilepsy and KD treatment, decreased fasting insulin and leptin levels were reported in children affected by Glut-1 deficiency syndrome and treated with a 3:1 KD, whereas adiponectin levels were unmodified." (PMID 24808888, 2014). "The effects of leptin have also been assessed in a penicillin model of epilepsy in the somatomoter cortex." (PMID 18024215, 2007). "Leptin and adiponectin, as two pivotal adipokines, act extensively in the central nervous system, and play an important role in the pathophysiology of different neurological diseases, including epilepsy." (PMID 36797447, 2023).
epilepsy (continued). "However, many scholars have devoted to study the regulatory mechanism of leptin and adiponectin which has provided unique insights and opened a new perspective for the pathogenesis and treatment of epilepsy." (PMID 36797447, 2023). "The interaction between peripheral metabolic hormones, such as leptin, and higher brain functions that could influence epilepsy allows to consider potential novel therapeutic alternatives to face this neurodegenerative condition." (PMID 30185147, 2018). "Our samples had lower adipose tissues and were thinner, which might be because of hormones’ discharge from adipose cells such as leptin that may decrease the threshold of epilepsies." (PMID 27057188, 2016). "Since ghrelin is a promising candidate in view of its modulatory properties in seizures, the changes in this hormone regulation found in patients with epilepsy are of major interest, whereas other changes in peptide hormone regulation, involving leptin, galanin, and NPY, must be clearly defined." (PMID 24808888, 2014). "A KD modulates leptin, ghrelin, and melatonin plasma levels and gene expression in the brain, which suggests that these endocrine regulatory molecules have neuroprotective or antiepileptic effects in epilepsy and serve as potential markers of antiepileptic drug responses." (PMID 31440210, 2019). "Therefore, it is important to conduct more studies to determine the influence of leptin on the pathophysiology of epilepsy to better understand its mechanism of action and to shed light on its therapeutic potential and its possible benefits when compared with AEDs." (PMID 30185147, 2018). "In particular, peptide hormones such as adiponectin, ghrelin, and leptin and neuropeptides such as CCK, galanin, NPY, and somatostatin appear to be promising candidates for future research on new treatments for epilepsy." (PMID 24808888, 2014). "By correlating co-expressed genes as well as immune cell ratios, we obtained genes with significant correlation with immune cell ratios (SIRPA, AKR1A1, LEP, ALDOA) that will be validated in epilepsy data at the single cell level in an attempt to find immune genes that link heart and brain tissue." (PMID 36776884, 2023). "Several peripheral peptide hormones involved in the control of food intake and metabolism (e.g., leptin, adiponectin, NPY, insulin, ghrelin) that are influenced by the KD also possess antiseizure properties and, as such, are promising candidates for future research on new treatments for epilepsy." (PMID 35276837, 2022).